SNORA24B (small nucleolar RNA, H/ACA box 24B)
Gene: Small nucleolar RNA gene on chromosome 15 (65,285,461 to 65,285,591, reverse strand). Ensembl gene ENSG00000206903.
Gene Ontology:
Biological process: RNA processing
Cellular component: nucleolus
Homologues: Orthologues: chimpanzee SNORA24B (100% identical), macaque SNORA24B (96% identical). Paralogues in human: SNORA24 (94% identical).